DUSP1 (dual specificity phosphatase 1)
Diseases named in the same sentence as DUSP1 in open-access papers (continued):
Sharing a sentence is not in itself a finding about the gene and the disease.
renal fibrosis (11 papers, 2020 to 2025). A final common manifestation of a wide variety of chronic kidney diseases characterized by glomerulosclerosis and tubulointerstitial fibrosis. "DUSP1 deficiency exacerbated UUO-induced renal fibrosis in mice, whereas overexpression of DUSP 1 reduces fibrogenesis in human renal tubular epithelial (HK-2) cells treated with transforming growth factor-β1 in vitro." (PMID 40213676, 2025). "Dual-specificity phosphatase 1 (DUSP1), a regulator of mitogen-activated protein kinase (MAPK) pathways, is linked to diseases such as cancer and immune disorders, but its role in renal fibrosis is unclear." (PMID 40213676, 2025). "The role and mechanism of DUSP1-mediated inhibition of renal fibrosis was evaluated both in vivo and in vitro." (PMID 40213676, 2025). "This study aimed to clarify the role of DUSP1 in renal fibrosis, identify the intrinsic mechanisms involved, and provide a theoretical basis for the clinical translation of a new target for renal fibrosis treatment." (PMID 40213676, 2025). "Mechanistically, deletion of DUSP1 promotes the nuclear translocation of Smad3, a crucial mediator of renal fibrosis, primarily through dephosphorylation at its 423/425 residue." (PMID 40213676, 2025). "At the same time, lncRNA NR_038323 reduced the degree of renal fibrosis by targeting DUSP1, suggesting that DUSP1 is a potential therapeutic target for CKD with NAFLD." (PMID 36923221, 2023). "Dusp1 gene deletion significantly exacerbated renal function deterioration, renal tubular injury, renal fibrosis, mitochondrial damage, and the production of inflammatory cytokines induced by IRI." (PMID 37935658, 2023). "Dusp1 gene deletion exacerbated acute ischemic injury, post-ischemic renal fibrosis, and tubular mitochondrial dysfunction in mice." (PMID 37935658, 2023). "For example, the low expression of ferroptosis-related gene DUSP1 obtained by screening is related to glucose metabolism disorder, renal failure, renal hypertrophy, renal fibrosis, and glomerular apoptosis." (PMID 36466094, 2022). "Dual-specificity phosphatase 1 (DUSP1), a regulator of the MAPK family, is associated with various pathological changes in the kidney, including renal hypertrophy, renal fibrosis, and glomerular apoptosis." (PMID 36585417, 2022). "Ge et al23 also found that overexpression of the lncRNA NR_038323 regulated renal fibrosis via the miR‐324‐3p/DUSP1 axis in DN." (PMID 32969198, 2020). "We established a UUO-induced renal fibrosis model using DUSP1 knockout mice." (PMID 40213676, 2025). "Therapeutic strategies targeting DUSP1 and this pathway may offer therapeutic implications for ischemic kidney disease and subsequent renal fibrosis." (PMID 37935658, 2023). "Moreover, lncRNA NR_038323 is also revealed to suppress HG-induced renal fibrosis through the miR-324-3p/DUSP1 axis." (PMID 35443864, 2022). "NR-038323 induced by HG via miR-324-3p/DUSP1/p38MAPK and ERK1, 2 regulations could mitigate renal fibrosis." (PMID 36035118, 2022). "In STZ-induced DKD mice, lncRNA NR_038323 may interact with miR-324-3p, which upregulates the expression of dual-specificity protein phosphatase-1 (DUSP1), downregulates the expression of collagen I, collagen IV and fibronectin, and significantly improves renal fibrosis and glomerular hypertrophy." (PMID 37455912, 2023). "Additionally, decreased expression of DUSP1 may lead to overactivation of MAPK and JNK signaling pathways, which can stimulate fibroblast proliferation and collagen synthesis, thereby promoting the progression of diabetic kidney disease and renal fibrosis." (PMID 37935658, 2023).
cardiac hypertrophy (10 papers, 2019 to 2025). "A decreased DUSP1 expression showed an association with diabetes-associated cardiac hypertrophy." (PMID 36080217, 2022). "DUSP1, CCND1, STAT3, and THBS1 play important roles in the pathological process of hypertrophic cardiomyopathy (HCM), regulating myocardial hypertrophy, fibrosis, and cardiac remodelling through a complex signalling network." (PMID 40427439, 2025). "In cardiomyocytes treated with high glucose, the inhibition of miR-200c-3p led to the overexpression of DUSP1 and the low expression of p-ERK1/2, p-P38, and p-JNK, thus attenuating the cardiac hypertrophy." (PMID 35299961, 2022). "In the heart, DUSP1 regulates cardiac metabolism, and the inhibition of DUSP1 (or MKP1) was reported to induce cardiac hypertrophy in a transgenic mouse model." (PMID 31438862, 2019).
colon cancer (10 papers, 2011 to 2025). "As far as colon cancer (CC) is concerned, although an early study reported that DUSP1 is overexpressed in the initial stages of carcinogenesis and gradually downregulated during tumour progression, several lines of evidence point to a protumoural role of DUSP1 in CC." (PMID 40943262, 2025). "In vitro, DUSP1 overexpression induced apoptosis at colon cancer cells." (PMID 21547253, 2011). "In colon tumor tissue, similar gene expression changes were found for CYR61, RGS1, DUSP1, DUOX2, and SLC6A14, although the log-fold change was generally lower compared to normal tissue." (PMID 25526028, 2014).
diabetes (10 papers, 2014 to 2025). "It was found to induce diabetes-associated cardiac hypertrophy by down regulating expression of dual-specific phosphatase-1 (DUSP-1)." (PMID 29085333, 2017). "Furthermore, and after adjustment for the usual risk factors using multivariate analyses, DUSP1 exhibited a relatively strong association with CVD (OR = 2.277) despite the possible confounding factors in our study (diabetes and statin treatment)." (PMID 30647800, 2018). "The research also referred to changes in global gene expression within the dorsal root ganglion (DRG) sensory neurons in diabetes, introducing differentially expressed mRNAs and their potential therapeutic implications, such as CWC22 and DUSP1, in improving neuropathic features in diabetes." (PMID 38928135, 2024). "Additionally, diabetes‐induced reduction in Dusp1 mRNA and protein levels was recovered by glucocorticoid treatment." (PMID 31328390, 2019). "More interestingly, when subjects were clustered by statin treatment or diabetes, the highest circulating levels of DUSP1 were observed in the group without statin treatment and in CVD patients without diabetes." (PMID 30647800, 2018).
glioblastoma (10 papers, 2013 to 2025). The most malignant astrocytic tumor (WHO grade IV). "As reviewed earlier, dysregulation or mutations of PTEN, PP2A, CDC25, and DUSP1 in glioblastoma modulate glioblastoma initiation, development, progression, and recurrence." (PMID 41158869, 2025). "DUSP1 expression is decreased in glioblastoma-derived tumour stem cells (TSCs), but increased expression induces TSC differentiation." (PMID 40867253, 2025). "In this study, we have identified that MKP1/DUSP1 expression is heterogeneous within low- and high-grade gliomas and particularly in glioblastoma samples." (PMID 29284798, 2017). "As Markov blanket genes, DUSP1 was common in Pilocytic and Diffuse tumors; EIF4A1 was common in Pilocytic, Diffuse and Anaplastic tumors; MARCKs was common in Diffuse and Anaplastic tumors and SERBP common in Anaplastic and Glioblastoma tumors." (PMID 23737970, 2013). "The expressions of DUSP1, DUSP5, and DUSP6 were predominantly reported in pseudopalisading and perinecrotic regions of the GBM aggressive tumor, as reported in the Ivy Glioblastoma (GBM) Atlas Project (Ivy GAP) repository." (PMID 41158869, 2025).
head and neck squamous cell carcinoma (10 papers, 2015 to 2025). A squamous cell carcinoma that arises from any of the following anatomic sites: lip and oral cavity, nasal cavity, paranasal sinuses, pharynx, larynx, and salivary glands. "In the study on head and neck squamous cell carcinoma, cannabinoids were able to stimulate dual specificity phosphatase 1 (DUSP1), which is a negative regulator of MAPK." (PMID 36291926, 2022). "In head and neck squamous cell carcinoma, DUSP1 suppresses carcinogenesis via decreasing IL-1β expression in tumor pro-inflammatory microenvironment." (PMID 29558404, 2018). "The other gene, DUSP1, functions as a pro-inflammatory mediator and has been found in head and neck squamous cell carcinoma, which could in turn be stimulated by multiple pro- and anti-inflammatory stimuli." (PMID 26461477, 2015). "DUSP1 expression is decreased in OSCC, and DUSP1 downregulation promotes the progression of head and neck squamous cell carcinoma." (PMID 40415961, 2025). "Notably, in head and neck squamous cell carcinoma (HNSCC), the CCR7/DUSP1 signaling axis regulates iCAFs activity, enhancing tumor cell growth potential." (PMID 40755775, 2025).
psoriasis (10 papers, 2013 to 2024). An autoimmune condition characterized by red, well-delineated plaques with silvery scales that are usually on the extensor surfaces and scalp. "This study highlights the involvement of DUSP1 in regulating proliferation and apoptosis in HaCaT cells and offers insights into its potential role in psoriasis pathogenesis." (PMID 38892253, 2024). "In psoriasis, DUSP1 expression is notably reduced in psoriasis-inducing cocktail-treated dermal mesenchymal stem cells and HaCaT cells." (PMID 38892253, 2024). "The negative regulator DUSP1/MKP-1 is downregulated in psoriasis, and its overexpression inhibits keratinocyte proliferation by targeting the ERK pathway." (PMID 38892253, 2024). "Studies of psoriasis or colitis have shown that down-regulation of DUSP1 promotes the occurrence of these diseases, and DUSP1 may be a target for disease treatment." (PMID 36985341, 2023). "Interestingly, the p38 MAPK-negative-feedback mechanism provided by DUSP1 seems to be impaired in psoriasis since DUSP1 mRNA expression was significantly downregulated in psoriatic skin lesions compared to nonlesional psoriatic skin." (PMID 24151518, 2013). "It presents molecular targets such as high-mobility group box-1 (HMGB1), dual-specificity phosphatase-1 (DUSP1), and the aryl hydrocarbon receptor (AhR) for treating psoriasis." (PMID 38892253, 2024). "Additional shared signatures between ILCs and T cells were related to genes that regulate tissue residency (FOS and NR4A1; module 18) as well as quiescence (TSC22D3, DUSP1, ZFP36L2, and KLF6; module 22), the latter recently shown to be expressed by plastic skin ILCs in a mouse model of psoriasis." (PMID 37160121, 2023). "We demonstrated a potential relationship between DUSP1 and miR-34a; DUSP4 and miR-34a, miR-382, and miR-3188; MAPK9 and miR-1275, MAP2K7 and mir-200-5p; MAP3K2 and mir-200-5p, which may be the subject of further research in the context of psoriasis." (PMID 38445655, 2024). "Nevertheless, we demonstrated a potential relationship between DUSP1 and miR-34a; DUSP4 and miR-34a, miR-382, and miR-3188; MAPK9 and miR-1275, MAP2K7 and mir-200-5p; MAP3K2 and mir-200-5p, which may be the subject of further research in the context of psoriasis." (PMID 38445655, 2024).
bladder cancer (9 papers, 2017 to 2025). "Interestingly, AREG, ATF3, ZFP36, and DUSP1 were all associated with inflammation and cancer, specifically enrichment of adipocytokine signaling, bladder cancer, epithelial cell signaling in Helicobacter pylori infection, and JAK/STAT signaling pathways in patients with high AREG expression." (PMID 35372438, 2022). "The study revealed that exosomal miR-133b significantly reduced the viability and increased apoptosis in bladder cancer cells by upregulating dual-specificity protein phosphatase 1 (DUSP1), a key regulator of cell proliferation and apoptosis." (PMID 40395335, 2025). "On the other hand, overexpressed LINC00702 leads to inhibited proliferation of bladder cancer cells by targeting DUSP1 in vitro." (PMID 39345881, 2024). "In early prostate and bladder cancers, DUSP1 is expressed at higher levels, however, as histological grade progresses, DUSP1 levels decrease." (PMID 34425899, 2021). "For example, DUSP1 display a decreased expression in high histological grade tumors including prostate, colon, and bladder cancer." (PMID 31052457, 2019). "Thus, LINC00702-activated DUSP1 suppresses bladder cancer cell proliferation and inhibits the secretion of inflammatory cytokines IL-4, IL-10, and TNF-α M2-OAM in bladder cancer." (PMID 38139370, 2023). "Overexpression of DUSP1/MKP1 has been observed in several human epithelial tumors, including prostate, colon and bladder cancers." (PMID 28129656, 2017). "DUSP1 is activated by phosphorylation on two Serine residues, Ser359 and Ser364 by ERK1/2 in human embryonic kidney (HEK) 293 cells; on the other hand, DUSP1 inactivates ERK1/2 by dephosphorylation in human bladder cancer HT1197 cells." (PMID 29383165, 2017).
colorectal cancer (9 papers, 2012 to 2025). A primary or metastatic malignant neoplasm that affects the colon or rectum. "Among the upregulated target genes, we highlighted six that are closely linked to colorectal cancer: LGALS9, GLUT1, IGFBP3, CDK4, DUSP1, and HIF1A." (PMID 41411347, 2025). "Furthermore, AB has been shown to significantly upregulate dual-specificity phosphatase 1 40 or enhance the expression of NKG2D ligands on colorectal cancer cells, thereby sensitizing natural killer-mediated cancer immunotherapy." (PMID 39629122, 2024). "The DUSP1 transcript was dramatically decreased in colorectal cancer compared to normal cells." (PMID 23320178, 2012). "Together, these findings indicate that CEBPB directly targets the DUSP1 promoter and modulates its transcriptional activity, thereby providing mechanistic insight into how CEBPB influences key signaling pathways in colorectal cancer." (PMID 41411347, 2025).
diabetic nephropathy (9 papers, 2022 to 2026). "Previous experimental studies have shown that DUSP1 has an improving effect on diabetic nephropathy." (PMID 40852352, 2025). "M2 macrophages activate autophagy in foot cells of diabetic nephropathy (DN) induced by high glucose through the secretion of exosomal miR-25-3p, which suppresses the expression of DUSP1." (PMID 38609925, 2024). "The role of DUSP1 has been suggested in few studies regarding kidney diseases, and previous experimental studies reported that DUSP1 ameliorates diabetic kidney diseases." (PMID 35488446, 2022). "Recent studies revealed that DUSP1 positively modulates Parkin-related mitophagy during diabetic nephropathy 30, although the underlying molecular basis has not been clearly demonstrated." (PMID 37063418, 2023). "This strategy would be particularly important in diabetic kidney diseases, in which the role of DUSP1 has also been identified by in vivo experiments, and direct modification of DUSP1 may reduce inflammatory injury while avoiding the metabolic side effects of glucocorticoids." (PMID 35488446, 2022).
Insulin resistance (9 papers, 2010 to 2025). Increased resistance towards insulin, that is, diminished effectiveness of insulin in reducing blood glucose levels. "The overexpression of Dusp1, Insig2, and Lcn2 has been linked to the development of insulin resistance." (PMID 21187916, 2010). "Moreover, chronic high glucose-induced insulin resistance is accompanied with marked reductions in DUSP1 induction." (PMID 30647800, 2018). "Another mechanism that might mediate glucocorticoid-induced insulin resistance is the induction of Mkp-1 (a.k.a Dusp1) by glucocorticoids." (PMID 30310815, 2018).
osteosarcoma (9 papers, 2019 to 2025). A usually aggressive malignant bone-forming mesenchymal neoplasm, predominantly affecting adolescents and young adults. "The association of DUSP1 and miR-34a has previously appeared in relation to osteosarcoma and pulmonary artery smooth muscle cells." (PMID 38445655, 2024). "Their study demonstrated that Siglec-15 promoted the migration and invasion of osteosarcoma cells via the DUSP1-inactivated MAPK pathway." (PMID 35842729, 2022). "Relationship between clinicopathologic parameters and Siglec-15 and DUSP1 expression in human osteosarcoma tissues." (PMID 34336699, 2021). "DUSP1 gene silencing has been shown to increase the expression of MAPK7 and MAPK8 transcripts in osteosarcoma cells suggesting reciprocal actions between them." (PMID 31035605, 2019).
cardiac ischemia (8 papers, 2014 to 2025). "Another study revealed that DUSP1 was down-regulated by acute cardiac ischemia/reperfusion injury and loss of DUSP1 led to the activation of mitophagy, during which the reintroduction of DUSP1 alleviated mitophagy." (PMID 40799529, 2025). "DUSP1 deficiency was reported to exacerbate cardiac ischemia/reperfusion injury by activating mitochondrial fission through mitochondrial fission factor in a manner dependent on the c-Jun N-terminal kinase pathway." (PMID 38322592, 2024). "We previously demonstrated that DUSP1 is critically important for mitochondrial quality control in cardiac ischemia/reperfusion injury 26 and endotoxemia-related myocardial dysfunction." (PMID 38322592, 2024). "USP49 has been reported to deubiquitinate DUSP1, which mediates the DUSP1-JNK signaling pathway and plays a protective role in cardiac ischemia/reperfusion (I/R) injury." (PMID 35279684, 2022).
glioma (8 papers, 2017 to 2024). A benign or malignant brain and spinal cord tumor that arises from glial cells (astrocytes, oligodendrocytes, ependymal cells). "This study also showed that the overexpression of DUSP1 in glioma cell lines significantly reduces cellular growth in vitro and in vivo, mainly by suppressing the proliferation and self-renewal ability of the glioma stem cells niche." (PMID 31018603, 2019). "The use of a FAK inhibitor in glioma cells increases expression of DUSP1 and DUSP5, suggesting the existence of a negative feedback loop." (PMID 29022062, 2018).